E2F3 (E2F transcription factor 3)
Description:
Transcription activator that binds DNA cooperatively with DP proteins through the E2 recognition site, 5'-TTTC[CG]CGC-3' found in the promoter region of a number of genes whose products are involved in cell cycle regulation or in DNA replication. The DRTF1/E2F complex functions in the control of cell-cycle progression from G1 to S phase. E2F3 binds specifically to RB1 in a cell-cycle dependent manner. Inhibits adipogenesis, probably through the repression of CEBPA binding to its target gene promoters (By similarity).
Synonyms: E2F-3
Tractability: PROTAC: ubiquitination databases record sites on it. Other modalities: a drug acting on it is in phase 2 or 3 trials.
Gene: Protein-coding gene on chromosome 6 (20,401,847 to 20,493,714, forward strand). Ensembl gene ENSG00000112242.
Subcellular location: Nucleus
Subcellular location (Human Protein Atlas): Nucleoplasm
Pathways (Reactome):
Cell Cycle: Cyclin D associated events in G1; G2 Phase
Cellular responses to stimuli: Oncogene Induced Senescence; Oxidative Stress Induced Senescence
Disease: Defective binding of RB1 mutants to E2F1,(E2F2, E2F3)
Signal Transduction: Pre-NOTCH Transcription and Translation
Gene Ontology:
Molecular function: cis-regulatory region sequence-specific DNA binding; DNA-binding transcription activator activity, RNA polymerase II-specific; protein binding; RNA polymerase II transcription regulatory region sequence-specific DNA binding; sequence-specific DNA binding; sequence-specific double-stranded DNA binding; DNA-binding transcription factor activity; DNA-binding transcription factor activity, RNA polymerase II-specific; RNA polymerase II cis-regulatory region sequence-specific DNA binding; DNA binding; protein dimerization activity
Biological process: G1/S transition of mitotic cell cycle; positive regulation of transcription by RNA polymerase II; positive regulation of vascular associated smooth muscle cell apoptotic process; protein import into nucleus; negative regulation of fat cell proliferation; regulation of transcription by RNA polymerase II; transcription initiation at RNA polymerase II promoter; regulation of DNA-templated transcription
Cellular component: nucleoplasm; nucleus; RNA polymerase II transcription regulator complex; chromatin; transcription regulator complex
Genetic constraint (gnomAD): Loss-of-function variants: 8 observed, 36.69 expected, observed/expected ratio (o/e) 0.22, 90% interval 0.13 to 0.39. The upper end of that interval is the gene's LOEUF score, 0.39, which puts it in group 1 of 6, group 1 being the genes least tolerant of losing a copy. Missense variants: 468 observed, 556.85 expected, observed/expected ratio (o/e) 0.84, 90% interval 0.78 to 0.91. Synonymous variants: 241 observed, 243.07 expected, observed/expected ratio (o/e) 0.99, 90% interval 0.89 to 1.1.
Homologues: Orthologues: chimpanzee E2F3 (99% identical), macaque E2F3 (99% identical), pig E2F3 (98% identical), dog E2F3 (97% identical), rabbit E2F3 (97% identical), guinea pig E2F3 (96% identical), rat E2f3 (95% identical), mouse E2f3 (94% identical), tropical clawed frog e2f3 (64% identical), zebrafish e2f3 (46% identical). Paralogues in human: E2F2 (43% identical), E2F1 (37% identical), E2F4 (25% identical), E2F6 (24% identical), E2F5 (21% identical), E2F7 (19% identical), E2F8 (19% identical).
Diseases named in the same sentence as E2F3 in open-access papers:
E2F3 is named in the same sentence as 140 diseases in open-access papers, as found by Europe PMC text mining. Sharing a sentence is not in itself a finding about the gene and the disease. The quoted sentences say what the papers report.
bladder cancer (64 papers, 2008 to 2026). "Supporting its oncogenic role, E2F3 is focally amplified in bladder cancer, a genomic alteration associated with advanced disease and poor clinical outcomes." (PMID 40246827, 2025). "The amplification of this region, and specifically E2F3 in bladder cancer, was associated with tumor cell proliferation." (PMID 34439350, 2021). "In human bladder cancer, amplification of the E2F3 gene, located at 6p22, is associated with overexpression of its mRNA and high expression of the E2F3 protein." (PMID 30072631, 2018). "Similarly, miR-125b–which suppresses oncogenic transcription factor E2F3 and is associated with cellular aging–is downregulated in bladder cancer, leading to overexpression of E2F3 and accelerated tumor cell proliferation." (PMID 40918525, 2025). "Furthermore, down-regulation of hsa-miR-194-5p expression was closely associated with E2F3 up-regulation and node metastasis in bladder cancer." (PMID 38342922, 2024). "In this study, we demonstrate that E2F3 directly activates the transcription of TACC3 in bladder cancer." (PMID 40246827, 2025). "And lncRNA RBAT1 promotes tumor initiation by interacting with and activating HNRNPL and E2F3 in bladder cancer, respectively." (PMID 39539669, 2024). "In bladder cancer, E2F3 is inextricably related to its initiation, and overexpression of E2F3 can culminate in tumorigenesis." (PMID 37253635, 2023). "For instance, the overexpression of E2F1, E2F2, and E2F3 was observed in patients with hepatocellular cancer, bladder cancer, retinoblastoma, and liposarcoma." (PMID 35392496, 2022). "QKI-6 inhibits the malignant behavior of bladder cancer cells through down-regulating E2F3 and NF-κB signaling." (PMID 33854603, 2021). "As they are regulated by transcription factors E2F1 and E2F3, these two genes are also down-regulated in bladder cancer." (PMID 33855049, 2021). "In bladder cancer, depletion of RB transcriptional corepressor 1 activates the E2F3, Myc, and mTOR signaling pathways to facilitate proliferation and restrain apoptosis of cancer cells." (PMID 34644734, 2021). "The specific mechanism of action between related miRNA and E2F3 has been reported in the literature on hepatocellular carcinoma, bladder cancer, ovarian cancer, LUAD, and gastric cancer." (PMID 32598517, 2020). "Previous study has indicated that E2F3 was highly expressed and contributed to tumor progression in a variety of tumors, such as colorectal, melanoma and bladder cancer." (PMID 32669100, 2020). "E2F3 is a transcription factor involved in cell proliferation and cycle regulation, and highly expressed in bladder cancer, prostate cancer, and liver cancer." (PMID 31582908, 2019). "In conclusion, we demonstrated that QKI‐6 down‐regulation in bladder cancer tissues and cells promoted tumour cell malignant behaviours by down‐regulating E2F3 and NF‐κB signalling pathways." (PMID 31449345, 2019). "Future studies are needed to clarify the specific mechanism by which QKI‐6 regulates E2F3 and NF‐κB signalling in bladder cancer development and progression." (PMID 31449345, 2019). "Proliferation of the 5637-bladder cancer cell line was found to be highly dependent on the 6p22.3 amplicon, particularly of the E2F3 gene." (PMID 30072631, 2018). "There is now evidence that E2F3 in 6p22-amplified bladder cancer is a potential oncogene of critical importance." (PMID 30072631, 2018). "Bladder carcinomas selectively down-regulate miR-503 and miR-125b that cooperate with Pumilio to target E2F3, and multiple tumor cell lines shorten the 3′-end of the E2F3 mRNA, removing the Pumilio regulatory elements." (PMID 30018188, 2018). "The amplicon in chromosome 6 contains SOX4 and E2F3 and is frequently found amplified in bladder cancer." (PMID 30072631, 2018). "E2F3 has been known to be significant with tumour stages, grades and cell proliferation in bladder cancer and significant with tumour aggressive in prostate cancer." (PMID 30487158, 2018).
bladder cancer (continued). "Because of the role E2F3 in cell cycle progression, these findings support that the E2F3 gene represents a candidate bladder cancer oncogene activated by DNA amplification and overexpression." (PMID 30072631, 2018). "It was demonstrated that miR-200c was significantly diminished in bladder cancer tissues and appeared to control the EMT process of bladder cancer cells via regulation of BMI-1 and E2F3." (PMID 28947999, 2017). "MiR-200c was shown to inhibit invasion, migration, and proliferation of bladder cancer cells through down-regulation of BMI-1 and E2F3." (PMID 28978061, 2017). "MiR-200c also target polycomb complex protein BMI-1 and E2F transcription factor 3 (E2F3) to inhibit bladder cancer cell migration and proliferation." (PMID 27058893, 2016). "In urinary bladder cancer, amplification of 6p22 sequences that included E2F3 was concerned with higher cancer cell proliferation rates." (PMID 27027446, 2016). "Fetal hepatocytes have high IGF2 and E2F3 expressions, and levels of IGF2 and E2F3 mRNA were positively correlated to human prostate and bladder cancers." (PMID 25580437, 2014). "miR-200c appears to control the EMT process through BMI-1 in bladder cancer cells, and it inhibits their proliferation through down-regulating E2F3." (PMID 25367080, 2014). "In this study, we found that down-regulated expression of miR-200c and up-regulation of its direct target BMI-1 and E2F3 in bladder cancer tissue and cell lines." (PMID 25367080, 2014). "The current study has indicated that miR-200c is a tumor-suppressive miRNA in bladder cancer, and that oncogene and transcription promoters, namely, BMI-1 and E2F3, are functional targets of miR-200c." (PMID 25367080, 2014). "In our study, we found that E2F3 was down-regulated in the miR-200c over-expression bladder cancer cell lines and consequently the proliferation was inhibited which was proved by CCK-8 assay and clone formation assay." (PMID 25367080, 2014). "E2F3 is a member of the E2F family that is often dysregulated during tumorigenesis and over-expressed in a variety of cancers, including bladder cancer." (PMID 25367080, 2014). "For example, proliferation advantage of the 5637 bladder cancer cell line is highly dependent on the 6p22.3 amplicon, in particular, the E2F3 gene within the locus, and knockdown of E2F3a or E2F3b significantly reduced cell proliferation." (PMID 24231253, 2013). "In summary, we have provided evidence that E2F3 in 6p22-amplified bladder cancer is a potential oncogene of importance." (PMID 24231253, 2013). "In summary, our data indicate that E2F3 is a key regulator of cell proliferation in a subset of bladder cancer and the 6p22.3 amplicon is a biomarker of aggressive phenotype in this tumor type." (PMID 24231253, 2013). "E2F3 levels are known to be regulated by pRb and have a crucial role in activating cell proliferation in human bladder cancers." (PMID 20421977, 2010). "We have shown also E2F3 protein overexpression and a dramatic decrease of Rb protein in bladder cancers." (PMID 20421977, 2010). "Recently, Plk1 has been reported to be regulated by E2F3 transcription factor, a partner of pRb in the regulation of cell cycle transitions, in bladder cancer cells in addition to known E2F3 targets such as Cyclin A." (PMID 20003272, 2009). "In two recent studies knock down experiments of E2F3 in bladder cancer cells lines with 6p amplification was shown to strongly reduce cellular proliferation whereas a similar knock down of CDKAL1 did not have this effect." (PMID 18237450, 2008). "Furthermore, 12 out of 34 bladder cancer cell lines with E2F3 amplification, defined as log2(copy number) ≥1.3, exhibited higher levels of TACC3 mRNA expression." (PMID 40246827, 2025). "E2F3 amplification may represent a lineage-specific event in bladder cancer because amplification of this region rarely occurs in other epithelial tumor types (21% vs. 4.9% of 1932 nonurothelial epithelial tumors)." (PMID 38920737, 2024).
bladder cancer (continued). "Increased expression of E2F3 has been found with advanced tumor stage of human bladder cancer." (PMID 36072391, 2022). "Reportedly, E2F3 accelerates tumor progression both in vivo and in vitro, and its expression is increased in different tumor types, such as, lung cancer, prostate cancer, bladder cancer, and retinoblastoma." (PMID 34657558, 2021). "Five genes are amplified in > 5% of the corresponding TCGA cohorts: E2F3 (cytoband 6p22.3, 15.7% of bladder cancer), TFRC (3q29, 13.0% of head and neck cancers), MFSD3 (8q24.3, 7.9% of head and neck cancers, FKBP4 (12p13.33, 6.8% of ovarian carcinoma) and FBXL20 (17q12, 6.4% of gastric cancer)." (PMID 34313788, 2021). "In addition, activation of E2F3 was reported to expedite cell proliferation and migration and block apoptosis in bladder cancer by interacting with Rb." (PMID 32348429, 2020). "For example, miR-125b could block the colonies form of bladder cancer cells in vitro and to develop tumors in nude mice by targeting E2F3." (PMID 32117628, 2020). "The QKI‐6 and E2F3 feedback loop could potentially and synergistically maintain each other's expression in bladder cancer." (PMID 31449345, 2019). "It has found that interference of E2F3 gene expression could prevent the cell cycle of bladder cancer 5637 cells in G1 phase and promote apoptosis." (PMID 31582908, 2019). "The amplicon in chromosome 6 that contains SOX-4 and E2F3 is frequently found amplified in bladder cancer might be epigenetically regulated and might be a potential target for therapy." (PMID 30072631, 2018). "Several other studies revealed the potential roles of miR-200c in bladder cancer metastasis, and overexpression of miR-200c significantly inhibited invasion and migration of bladder cancer cells and led to conspicuous reduction of BMI-1 and E2F3." (PMID 28947999, 2017). "Additionally, upregulation of either miR-497 or miR-200c inhibits proliferation of bladder cancer cells by downregulating E2F3." (PMID 28947999, 2017). "Gene amplification is one of the mechanisms underlying the activation of proto-oncogenes such as ERBB2, CCND1, CCNE1, MDM2, and E2F3, which have been suggested as cancer driver genes in bladder cancers, based on their aberrant gene amplification and protein overexpression." (PMID 27902773, 2016). "MiR-125b was suggested to suppress the development of bladder cancer by targeting E2F3." (PMID 25889255, 2015). "Notably, E2F3 is over-expressed in almost all bladder cancer and cell lines, suggesting that E2F3 is important for human bladder cancer development." (PMID 25367080, 2014). "In bladder cancer, microRNA-125b inhibited colony formation in an in vitro cell model and in vivo tumor development in nude mice by targeting E2F3, which frequently showed overexpression in bladder cancer and had an expression inversely correlated with that of microRNA-125b." (PMID 25014919, 2014). "Our results revealed a close, direct association between expression of miR-200c, BMI-1, E-cadherin, N-cadherin, P14, P16 and E2F3 expression, representing a pivotal cellular axis impacting not only the capacity of bladder cancer cells to metastasize but also the ability of proliferation." (PMID 25367080, 2014). "We first examined the E2F3 protein level in a panel of bladder cancer cell lines." (PMID 24231253, 2013). "As previously reported, we also detected E2F3 as over expressed in bladder cancer." (PMID 23717626, 2013). "We extracted 82 putative targets of E2F3 from knock-down experiments in bladder cancer and found no overlap with the 78 E2F3 associated genes in NCI-60." (PMID 20925909, 2010). "Also Plk1 has been reported to be regulated by E2F3 in bladder cancer cells in addition to known E2F3 targets such as Cyclin A and novel targets including pituitary tumor transforming gene 1 (PTTG1), and Caveolin-2." (PMID 19883508, 2009). "Furthermore, QKI-6 could downregulate E2F3 and NF-κB signaling to inhibit bladder cancer malignant behaviors." (PMID 35600368, 2022).
bladder cancer (continued). "Moreover, in bladder cancer, it has been reported that miR-200c is downregulated in cancer specimens compared with adjacent tissues in the same patients, and miR-200c could inhibit bladder cancer cell invasion through direct targeting of BMI-1 and E2F3." (PMID 31240993, 2019). "The transcription factor E2F3 bound to the QKI-6 promoter to induce the transcription of QKI-6 and then controlled the occurrence and development of bladder cancer by regulating the cell cycle." (PMID 34504528, 2021). "Here, we use two types of E2F3-activated tumors, retinoblastoma and bladder cancer, to demonstrate that RBAT1 upregulation contributed to the activation of E2F3 in these tumor cells." (PMID 32669100, 2020). "A total of nine chr3p25 and chr11p11 genes were functionally connected to genes in the KEGG bladder cancer pathway (E2F1, E2F3, EGFR, RAF1, RB1) or to other cancer-related genes (AKT2, PIK3CA, RB1, TRIO)." (PMID 29140994, 2017). "Five genes in this network (E2F1, E2F3, EGFR, RAF1, and RB1) significantly overlapped genes in the bladder cancer pathway from the Kyoto Encyclopedia of Genes and Genomes (KEGG) database (FDR q<0.01)." (PMID 29140994, 2017). "Three of the most studied bladder cancer cell lines (T24, 5637, and HT1376), reflecting different molecular pathways for cell invasion (FGFR3/CCND1and E2F3/RB1), were chosen envisaging the identification of a ubiquitous reference gene." (PMID 27835695, 2016). "We have selected three bladder cancer cell lines (T24, 5637, and HT1376), representative of two distinct molecular pathways to invasive cancer (FGFR3/CCND1and E2F3/RB1), and widely explored by us in the establishment of novel therapeutic schemes." (PMID 27835695, 2016). "Accordingly, three bladder cancer cell lines (T24, 5637, and HT1376) representative of two distinct carcinogenesis pathways to invasive cancer (FGFR3/CCND1 and E2F3/RB1) were used." (PMID 27835695, 2016). "In a previous study, we reported that miRNA-143 and miRNA-125b act as tumor suppressors in human bladder cancer by binding to the oncogenes RAS and E2F3 respectively." (PMID 22768238, 2012). "For example, the expression of lncRNA retinoblastoma-associated transcript-1 (RBAT1) was significantly higher in both retinoblastoma (Rb) and bladder cancer (BCa) clinical tissues compared with normal tissues and RBAT promoted tumorigenesis by activating E2F3 transcription." (PMID 35568824, 2022). "miR-195 was shown to inhibit cyclin D1 in HCC and breast cancer, CCND3 in glioblastoma, CDK4 in bladder cancer, CDK6 in HCC, E2F3 in HCC and glioblastoma, BCL-2 in breast and colorectal cancer, RAF1 in breast cancer, and GLUT3 in bladder cancer." (PMID 23335942, 2012). "Furthermore, we have also tested HT1376, a bladder cancer cell line without E2F3 locus amplification." (PMID 32669100, 2020). "Besides, previous studies found that the down-regulation of miR-200c and miR-141 is associated with elevated ZEB1, and the down-regulation of miR-200c is also coupled with the down-regulation of BMI-1 and E2F3, which play an important role in the invasion, migration, and EMT of bladder cancer." (PMID 30323832, 2018).